IGF1 (insulin like growth factor 1)
Description:
The insulin-like growth factors, isolated from plasma, are structurally and functionally related to insulin but have a much higher growth-promoting activity. May be a physiological regulator of [1-14C]- 2-deoxy-D-glucose (2DG) transport and glycogen synthesis in osteoblasts. Stimulates glucose transport in bone-derived osteoblastic (PyMS) cells and is effective at much lower concentrations than insulin, not only regarding glycogen and DNA synthesis but also with regard to enhancing glucose uptake. May play a role in synapse maturation. Ca(2+)-dependent exocytosis of IGF1 is required for sensory perception of smell in the olfactory bulb (By similarity). Acts as a ligand for IGF1R. Binds to the alpha subunit of IGF1R, leading to the activation of the intrinsic tyrosine kinase activity which autophosphorylates tyrosine residues in the beta subunit thus initiating a cascade of down-stream signaling events leading to activation of the PI3K-AKT/PKB and the Ras-MAPK pathways. Binds to integrins ITGAV:ITGB3 and ITGA6:ITGB4. Its binding to integrins and subsequent ternary complex formation with integrins and IGFR1 are essential for IGF1 signaling. Induces the phosphorylation and activation of IGFR1, MAPK3/ERK1, MAPK1/ERK2 and AKT1. As part of the MAPK/ERK signaling pathway, acts as a negative regulator of apoptosis in cardiomyocytes via promotion of STUB1/CHIP-mediated ubiquitination and degradation of ICER-type isoforms of CREM (By similarity).
Synonyms: IGF-I; MGF; IGF1A; IGFI; IGF
Tractability: Small molecule: a structure with a bound ligand is known; it has a binding pocket of medium quality. Antibody: a drug acting on it is in phase 2 or 3 trials; its Gene Ontology location is reachable by antibodies, with high confidence; UniProt places it where antibodies can reach, with medium confidence; UniProt predicts a signal peptide or a membrane-spanning region. PROTAC: ubiquitination databases record sites on it.
Target class: Secreted protein
Gene: Protein-coding gene on chromosome 12 (102,395,874 to 102,481,744, reverse strand). Ensembl gene ENSG00000017427.
Subcellular location: Secreted
Pathways (Reactome):
Signal Transduction: IRS-related events triggered by IGF1R; SHC-related events triggered by IGF1R; Signaling by Type 1 Insulin-like Growth Factor 1 Receptor (IGF1R)
Metabolism of proteins: Regulation of Insulin-like Growth Factor (IGF) transport and uptake by Insulin-like Growth Factor Binding Proteins (IGFBPs); Synthesis, secretion, and deacylation of Ghrelin
Hemostasis: Platelet degranulation
Gene Ontology:
Molecular function: growth factor activity; hormone activity; insulin receptor binding; insulin-like growth factor receptor binding; integrin binding; protein binding; receptor ligand activity
Biological process: activation of protein kinase B activity; bone mineralization involved in bone maturation; cell activation; cell population proliferation; cell surface receptor signaling pathway via STAT; cellular response to amyloid-beta; growth hormone receptor signaling pathway; insulin receptor signaling pathway; insulin-like growth factor receptor signaling pathway; muscle hypertrophy; myoblast differentiation; myoblast proliferation; myotube cell development; negative regulation of amyloid-beta formation; negative regulation of apoptotic process; negative regulation of extrinsic apoptotic signaling pathway; negative regulation of gene expression; negative regulation of interleukin-1 beta production; negative regulation of neuroinflammatory response; negative regulation of oocyte development; negative regulation of smooth muscle cell apoptotic process; negative regulation of tumor necrosis factor production; negative regulation of vascular associated smooth muscle cell apoptotic process; positive regulation of activated T cell proliferation; positive regulation of calcineurin-NFAT signaling cascade; and 46 more
Cellular component: alphav-beta3 integrin-IGF-1-IGF1R complex; extracellular region; insulin-like growth factor ternary complex; exocytic vesicle; insulin-like growth factor binding protein complex; platelet alpha granule lumen; glutamatergic synapse; neuronal dense core vesicle lumen; postsynapse; secretory granule
Genetic constraint (gnomAD): Loss-of-function variants: 4 observed, 13.56 expected, observed/expected ratio (o/e) 0.3, 90% interval 0.14 to 0.68. The upper end of that interval is the gene's LOEUF score, 0.68, which puts it in group 2 of 6, group 1 being the genes least tolerant of losing a copy. Missense variants: 104 observed, 185.04 expected, observed/expected ratio (o/e) 0.56, 90% interval 0.48 to 0.66. Synonymous variants: 73 observed, 71.9 expected, observed/expected ratio (o/e) 1.02, 90% interval 0.84 to 1.23.
Homologues: Orthologues: guinea pig IGF1 (95% identical), mouse Igf1 (92% identical), chimpanzee IGF1 (91% identical), macaque IGF1 (91% identical), rabbit IGF1 (88% identical), dog IGF1 (88% identical), pig IGF1 (88% identical), rat Igf1 (76% identical), tropical clawed frog igf1 (76% identical), zebrafish igf1 (54% identical). Paralogues in human: IGF2 (37% identical), INS (22% identical).
Diseases named in the same sentence as IGF1 in open-access papers:
IGF1 is named in the same sentence as 1,177 diseases in open-access papers, as found by Europe PMC text mining. Sharing a sentence is not in itself a finding about the gene and the disease. The quoted sentences say what the papers report.
Insulin resistance (1,059 papers, 2007 to 2026). Increased resistance towards insulin, that is, diminished effectiveness of insulin in reducing blood glucose levels. "In women, diminished IGF-1 signaling together with poor nutritional status increases susceptibility to insulin resistance and sarcopenia." (PMID 41598223, 2026). "This is supported by the fact that abnormal IGF-1 levels are associated with insulin resistance, which worsens stroke outcome." (PMID 41094027, 2026). "Insulin resistance and IGF1 are also thought to play an important role in ABCD‐linked PCa risk via PI3/AKT, FOXO3A, and BIM signaling, causing angiogenesis, cell survival, growth, and invasion." (PMID 41450167, 2026). "In Danish adults (n=3,354), IGF-1 displayed a U-shaped relationship with insulin resistance, with both low and high levels linked to elevated HOMA-IR." (PMID 41393761, 2025). "Insulin resistance and the compensating hyperinsulinaemia cause elevated plasma IGF‐1 that can also stimulate prostatic growth." (PMID 40955380, 2025). "In obesity, diminished IGF-1 signaling is linked to dyslipidemia, hypertension, insulin resistance, type 2 diabetes, and cardiovascular disease." (PMID 40864762, 2025). "Hyperinsulinemia and insulin resistance, common in individuals with obesity, further elevate cancer risk by increasing circulating insulin-like growth factor 1 (IGF-1), which has mitogenic and anti-apoptotic properties." (PMID 40469681, 2025). "Insulin resistance is associated with hyperinsulinemia and insulin-like growth factor-1 (IGF-1) levels, which activate downstream insulin receptor substrates and key oncogenic signaling cascades, including the PI3K/AKT/mTOR and MAPK/ERK pathways." (PMID 41531579, 2025). "One study showed that HSI was associated with insulin resistance and reduced levels of growth hormone and insulin-like growth factor 1 in patients with acromegaly." (PMID 40642238, 2025). "Among the modifiable risk factors is obesity which promotes insulin resistance, hyperinsulinemia, and high levels of insulin-like growth factor-1 (IGF-1); all of which stimulate cell proliferation." (PMID 40607405, 2025). "Insulin resistance associated with obesity results in elevated insulin and insulin-like growth factor 1 (IGF-1) levels, which activate PI3K-AKT and (Mitogen-Activated Protein Kinase) MAPK signaling pathways critical for cell proliferation and survival." (PMID 41301707, 2025). "In conclusion, in insulin resistance and obesity, upregulation of IGF-1 signaling improves glucose uptake and supports the loss of body weight by increasing the unliganded activation of ERs." (PMID 41514592, 2025). "Oestrogen excess increases the risk of breast and endometrial cancers, while insulin resistance activates the insulin/IGF‐1 pathway, promoting colorectal cancer progression." (PMID 40944359, 2025). "Holstein cows, known for their genetic predisposition to insulin resistance due to high milk production, often have altered ovarian follicular dynamics after calving, with reduced concentrations of insulin and IGF-1." (PMID 40725447, 2025). "Acromegaly predisposes to insulin resistance, and the diabetogenic effect of GH would seem to outweigh the insulin-sensitizing effect of IGF-1." (PMID 40088375, 2025). "Insulin resistance, loss of IGF-1, and heightened cortisol often occur during this transition as well." (PMID 40884186, 2025). "IGF-1 was inversely associated with age, glycemic markers (fasting glucose, HbA1c), insulin resistance (HOMA-IR), TNF-α, and atherogenic lipids, while higher levels were linked to better insulin sensitivity." (PMID 41393761, 2025). "The current findings underline the significance of central IGF-1 signaling in the mechanisms and outcomes of brain insulin resistance, confirming its protective role against spatial memory deficits in sAD." (PMID 40283962, 2025). "Insulin resistance in the human brain affected by Alzheimer disease is also associated with brain IGF1 resistance." (PMID 40105689, 2025).
Insulin resistance (continued). "IGF-1 loss with age is also attributed to estradiol loss, increasing pathologies of insulin resistance." (PMID 40884186, 2025). "In our study, IGF-1 showed inverse associations with age, diabetes duration, blood pressure, glycemia, insulin resistance, and inflammation." (PMID 41393761, 2025). "Insulin resistance in these individuals causes hyperinsulinemia and higher levels of insulin-like growth factor-1 (IGF-1), predisposing them to carcinogenesis." (PMID 40929458, 2025). "Experimental studies further show that IGFBP-3 overexpression induces insulin resistance and dyslipidemia, while partial IGF-1 deficiency enhances gluconeogenic and lipogenic gene expression changes reversible with IGF-1 replacement." (PMID 41393761, 2025). "Muscle loss results in insulin resistance and increased activity of IGF-1, which can promote colorectal tumour progression." (PMID 39010859, 2024). "Hyperinsulinemia is a hallmark of insulin resistance, and hyperinsulinemia increases the production of IGF-1 significantly, which is related to the initiation and progression of multiple cancer types." (PMID 38339407, 2024). "Thirdly, deficiency of the GH/IGF-1 system produces leptin resistance, which leads to bulimia, obesity and subsequent insulin resistance, all of which contribute to early and aggressive hepatic steatosis." (PMID 38370349, 2024). "In patients under 9 years, only HOMA-IR was statistically associated with insulin resistance, while in the subgroup over 9 years, only IGF-1 and HOMA-IR were effectively associated with hyperinsulinemia." (PMID 38920551, 2024). "Lower IGF-1 levels have also been associated with other cardiovascular risk factors such as insulin resistance and obesity as well as poorer cognitive functioning." (PMID 39002108, 2024). "These derangements of somatotropic axis, reflected by low IGF-1 levels, are linked with insulin resistance, type 2 diabetes and cardiovascular disease." (PMID 39014246, 2024). "Insulin resistance can lead to increased levels of insulin and insulin-like growth factor 1 (IGF-1), which have been implicated in promoting the growth and proliferation of endometrial cells outside the uterus." (PMID 39199287, 2024). "During the pubertal period, the increased levels of sex hormones, growth hormone and insulin-like growth factor-1 are thought to cause the established physiological insulin resistance seen during puberty." (PMID 38386069, 2024). "Second, ageing is associated with lower IGF-1 and increased insulin resistance, and exposure to air pollutants has shown to be a risk factor of insulin resistance and reduced insulin sensitivity over time." (PMID 38303067, 2024). "SHBG, IGF-1, and Cortisol are all linked to glucose-lipid metabolism indices, and aberrant serum hormone expression is a major contributor to insulin resistance." (PMID 39876919, 2024). "Elevated serum level of GH/IGF-1 during puberty is positively associated with increased insulin resistance." (PMID 40302954, 2024). "Hyperinsulinemia caused by insulin resistance leads to higher levels of insulin-like growth factor 1, which has been proposed to contribute to a pro-tumoral microenvironment." (PMID 38972968, 2024). "Altered IGF-1 function has been implicated in the pathogenesis of insulin resistance and in several other diseases, such as autoimmune diseases, atherothrombosis, osteoporosis, and certain common types of cancer." (PMID 38255314, 2024). "We repeated the same analysis in male patients, finding that only IGF-1 was associated with insulin resistance." (PMID 38920551, 2024). "Insulin resistance leads to hyperinsulinemia and increased insulin-like growth factor 1 (IGF-1) levels, which can activate signaling pathways associated with cellular proliferation and aging, potentially affecting telomere dynamics." (PMID 39045323, 2024).
Insulin resistance (continued). "The study aimed to investigate the impact of insulin resistance and glycaemic control on IGF-1 levels and to assess other risk factors influencing IGF-1 in T2DM." (PMID 39578883, 2024). "vWAT is associated with insulin resistance and increased insulin-like growth factor-1 (IGF-1) levels, which in turn activates insulin/IGF signaling and can enhance fat collection by impairing glucose/lipid metabolism in CRC." (PMID 39125923, 2024). "Although physiologically IGF-1 improves glucose homeostasis, the chronic excess of GH in acromegaly that causes insulin resistance greatly exceeds the possible beneficial effects of IGF-1 on insulin sensitivity." (PMID 37628857, 2023). "The excessive secretion of GH can result in chronic hypersomatotropism that can cause acromegaly and insulin resistance due to the concomitant increase in insulin-like growth factor-1 (IGF-1)." (PMID 37370445, 2023). "After calving, most dairy cows experience a period of NEB that is associated with insulin resistance, reduced hepatic growth hormone (GH) receptor expression, decreased hepatic synthesis of IGF-1, and altered expression of most of the IGF binding proteins." (PMID 37373054, 2023). "Mutations result in elevated IGFBP3, IGFBP5, and high total IGF-1 but decreased free IGF-1 as well as insulin resistance and low bone mineral density." (PMID 37898658, 2023). "This profile in women consists of relatively higher GH levels, which causes insulin resistance, and lower IGF-1 levels, which mediates anabolism." (PMID 37223021, 2023). "In MetS, hyperinsulinemia caused by insulin resistance and subsequent hyperglycemia can trigger carcinogenesis by increasing the circulating levels of free insulin-like growth factor (IGF)-1." (PMID 37109290, 2023). "Low levels of insulin or IGF-1 and insulin resistance cause the inhibition of Akt phosphorylation and subsequent reductions in phosphorylated GSK3β, resulting in the degradation of β-catenin proteins." (PMID 37569816, 2023). "There is a possible explanation for the observed differences: PCOS is often associated with hyperinsulinemia and peripheral insulin resistance; moreover, it is well established that IGF1 acts similarly to insulin." (PMID 37658762, 2023). "Maintaining lower–normal glucose levels with lower insulin and IGF-1 levels is associated with improved health outcomes, decreasing risk of insulin resistance and T2DM, reducing chronic diseases, and also improving longevity and healthy ageing." (PMID 37958602, 2023). "This study aimed to analyze the association between IGF-1 levels and indices of MetS and insulin resistance in BC survivors." (PMID 37106164, 2023). "Over the past few years, research studies have investigated the potential role of insulin resistance and IGF-1 in the association between PCOS and EC." (PMID 37988160, 2023). "Studies have demonstrated that GH/IGF-1 levels in GHPA patients are closely associated with insulin resistance." (PMID 37818085, 2023). "Asprosin is known to change the antioxidant-oxidant balance by causing hyperinsulinemia and insulin resistance, thereby increasing the expression level of insulin-like growth factor 1 (IGF-1), which causes cancer formation and metastasis." (PMID 37846349, 2023). "The etiologic association between insulin resistance and acromegaly is mirrored by the correlations between insulin sensitivity markers and IGF-1 level; however, similar correlations with GH level are either not demonstrated or weaker." (PMID 36882643, 2023). "A marked reduction of growth promoting GH/IGF-1 and insulin characterized early postnatal life and a decrease in testosterone activity at puberty coupled with insulin-resistance lead to a male-specific deficiency by adulthood." (PMID 35025875, 2022). "Another link is through the IGF-1 pathway, where hyperinsulinemia causes androgen suppression, high levels of estrogen, and a rise in insulin resistance." (PMID 35399507, 2022).